MMP11 (matrix metallopeptidase 11)
Diseases named in the same sentence as MMP11 in open-access papers (continued):
Sharing a sentence is not in itself a finding about the gene and the disease.
breast tumors (13 papers, 2007 to 2025). "Given its relative simplicity and low cost, immunohistochemical evaluation of MMP-11 expression in tumor tissues offers a complementary prognostication tool, allowing for a more nuanced risk assessment, tailored follow-up of these early, hormone receptors positive, breast tumors." (PMID 38438841, 2024). "Breast tumors infiltrated by MMP-11+ mononuclear inflammatory cells are more likely to metastasize, have high levels of interleukin (IL)-1, IL-5, IL-6, IL-17, interferon (IFN), and NFB, and an increased CD68+/(CD3+CD20+) cell ratio at the invasive front." (PMID 39190284, 2024). "Histological analysis of human breast tumors has shown that the adipocytes present at their invasive front also expressed high levels of MMP-11 and IL-6, in contrast to adipocytes from healthy tissues where these proteins are absent." (PMID 35268073, 2022). "In breast tumors, adipocytes increased expression of matrix metalloproteinase-11 (MMP11), along with MMP1, MMP7, MMP10, and MMP14, involving in cisplatin resistance." (PMID 34095111, 2021). "Adipocytes adjacent to breast tumors display increased levels of matrix metalloproteinase-11 (MMP11), which inhibits pre-adipocyte differentiation and reverses mature adipocyte differentiation to maintain the invasive property of cancer cells." (PMID 32850459, 2020). "With regards to TIMP2:MMP expression, breast tumors seemed to be more consistent with an almost ubiquitous increase in MMP11 and a smaller number of patients exhibiting high MMP9 expression." (PMID 31882975, 2019). "Genes associated with breast tumor invasion (CTSV, MMP11) were significantly abundant in sub-population III with OR2W3 upregulation compared to other sub-populations." (PMID 31551495, 2019). "We next performed MMP-11 immunohistochemistry on the selected series of breast tumors." (PMID 38438841, 2024). "Indeed, it has been observed that adipocytes present in the human breast tumor invasive front are stimulated by cancer cells to express the matrix metalloproteinase 11 (MMP11), inducing adipocyte reprogramming and EM remodelling." (PMID 36361914, 2022). "We compared the differentially expressed genes between the four types of organ metastases and primary breast tumors and identified genes such as COL11A1, MMP11, and THBS2 as more frequently differentially expressed in metastatic sites." (PMID 40500539, 2025).
bladder cancer (11 papers, 2006 to 2025). "This study identified a new subgroup of CAFs characterized as MMP11+ mCAFs, which increases progressively with the advancement of bladder cancer and is associated with poor prognosis." (PMID 40552583, 2025). "In this study, a novel CAF subgroup, MMP11+ mCAF is identified, through single‐cell RNA sequencing, which accumulates progressively during bladder cancer progression and is significantly associated with poor prognosis." (PMID 40552583, 2025). "This study identified a novel fibroblast subset, MMP11+ mCAFs (matrix CAFs), which is associated with bladder cancer progression and poor prognosis." (PMID 40552583, 2025). "In this study, they confirmed that increasing MMP-11 levels is associated with tumor progression and poor survival in bladder cancer patients." (PMID 38203373, 2023). "Our study emphasizes the role of the MMP11+ mCAF in bladder cancer and identifies a potential therapeutic target for its treatment." (PMID 40552583, 2025). "Single‐cell RNA sequencing identifies MMP11+ CAFs as pro‐angiogenic cells accumulating during bladder cancer progression." (PMID 40552583, 2025). "The presented results suggest that MMP-11, as a secreted protein, is a promising biomarker in the diagnosis and prognosis of patients with bladder cancer." (PMID 38203373, 2023). "In this study, we identified six ECM-related genes (CTHRC1, MMP11, COL10A1, FSTL1, SULF1, and COL5A3) that were associated with bladder cancer occurrence, tumor stage, and prognosis based on the bladder cancer tumor samples." (PMID 35450397, 2022). "The MMP-11 biomarker is used to diagnose and predict bladder cancer." (PMID 38203373, 2023). "In this study, they analyzed the expression of MMP-11 in patients with bladder cancer." (PMID 38203373, 2023). "Interestingly, matrix metalloprotease 11 (MMP11) was directly regulated by both miR-139 strands, and knockdown of MMP11 attenuated the aggressive phenotype of bladder cancer cells." (PMID 33322675, 2020). "Based on the TCGA dataset, the expression levels of COL10A1, COL5A3, CTHRC1, MMP11, and SULF1 in the bladder cancer tissues were higher than those in the normal bladder tissues." (PMID 35450397, 2022). "CTHRC1, MMP11, and COL5A3 protein levels were increased in bladder cancer than in normal bladder samples." (PMID 35450397, 2022).
invasive breast carcinoma (10 papers, 2004 to 2023). A carcinoma that infiltrates the breast parenchyma. "MMP-11, which is also named stromelysin-3, was first shown to be highly expressed in stromal cells in invasive breast cancer." (PMID 34038440, 2021). "MMP-11, also named stromelysin-3 (SL-3), was first identified in stromal cells surrounding invasive breast carcinomas." (PMID 33228130, 2020). "Another article also identified that high level of MMP-11 was in relation to invasive breast carcinoma and worsened prognosis." (PMID 26270045, 2015). "Matrix metalloproteinase-11 (MMP-11) is also known as Stromelysin-3, and was initially identified in invasive breast carcinomas." (PMID 25423087, 2014). "Stromal reaction to invasive breast carcinoma was associated with increased expression of genes encoding ECM components, proteolytic enzymes and adhesion receptors, including COL11A1, COL10A1, COMP, MMP11, FN1 and MFAP2, consistent with the abundant stromal remodeling observed by histology." (PMID 21611158, 2011). "Moreover, MMP-11 may be an independent prognostic factor for invasive breast cancer patients." (PMID 26456994, 2015).
pancreatic cancer (9 papers, 2007 to 2025). "In pancreatic cancer cells, MMP11 is associated with cancer cell migration and invasion, and overexpression of MMP11 can promote the occurrence and development of pancreatic cancer." (PMID 32291953, 2020). "The qPCR results confirmed high expression of MMP11 in pancreatic cancer cell lines, and IHC also verified high expression of MMP11 in clinical pancreatic ductal adenocarcinoma tissues." (PMID 38572434, 2024). "The results showed that the mRNA expression of MMP11 was significantly upregulated in pancreatic cancer cell lines than in a normal pancreatic duct epithelial cell line, which is consistent with the results of previous studies." (PMID 38572434, 2024). "The results showed that MMP11 was highly expressed in pancreatic cancer cell lines, including MIAPaCa, Aspc-1, HPAF-2, Panc-1, SW 1990, and CFPAC-1 and we selected SW1990 cell lines in the subsequent cell experiments." (PMID 38572434, 2024). "Jungert revealed that Smad proteins and SP1 cooperatively regulate expression of a distinct set of TGF‐β target genes potentially involved in tumour progression, including MMP‐11, cyclin D1 and Smad7 in pancreatic cancer cells." (PMID 32729205, 2020). "Subsequently, CCK-8 and transwell assay demonstrated that knockdown of MMP11 significantly reduced cell proliferation and invasion of SW1990 cell lines in vitro, suggesting MMP11 might provide new therapeutic target for the treatment of pancreatic cancer." (PMID 38572434, 2024). "In addition, IHC results further confirmed elevated expression of MMP11 in pancreatic cancer tissues compared with adjacent tissues." (PMID 38572434, 2024). "The expression of five key genes (MMP11, COL10A1, SERPINE1, COL11A1, and EPYC) in normal pancreatic and pancreatic cancer cell lines were detected using qPCR." (PMID 38572434, 2024).
melanoma (7 papers, 2018 to 2025). A malignant, usually aggressive tumor composed of atypical, neoplastic melanocytes. "MMP11-high patients exhibited a trend toward prolonged overall survival (OS) in both melanoma (HR = 0.62, 95% CI 0.37–1.04, P = 0.07) and clear cell renal carcinoma (HR = 0.64, 95% CI 0.33–1.31, P = 0.19) cohorts." (PMID 40607407, 2025). "There is still limited knowledge on the roles of MMP-11 in malignant melanoma, with contradictory results." (PMID 39063046, 2024). "MMP7 and MMP11, primarily overexpressed in early-stage melanoma, may influence the immunogenic landscape by regulating cytokine processing and enabling immune evasion." (PMID 40604111, 2025). "Some authors report a link between MMP-11 expression and tumor progression, while others have found that it may play a role in the regression of malignant melanoma." (PMID 39063046, 2024). "qRT-PCR in A375 melanoma cells showed significant overexpression of MMP7, MMP11, and MMP14 compared to normal skin cells, further supporting their relevance in melanoma." (PMID 40604111, 2025). "Immunohistochemistry from the Human Protein Atlas confirmed moderate to strong protein expression of MMP7, MMP11, and MMP14 in melanoma tissues, consistent with transcriptomic findings." (PMID 40604111, 2025). "STRING-based analysis showed that MMP7, MMP11, and MMP14 formed dense interaction networks with other ECM-related genes, indicating their regulatory significance in SCC and melanoma progression." (PMID 40604111, 2025). "A deeper look into SKCM datasets via TCGA validation revealed that MMP7, MMP11, and MMP14 also exhibited high expression in primary melanoma tumors." (PMID 40604111, 2025). "Our findings suggest that MMP7 and MMP11 may serve as early-stage targets, whereas MMP14 could inform treatment strategies in advanced melanoma and SCC." (PMID 40604111, 2025).
oral cancer (7 papers, 2011 to 2025). "Moreover, in established human oral cancer cell lines, we further evaluated the migration capability in MMP-11 overexpressed OSCC cell lines and the underlying mechanisms." (PMID 28427180, 2017). "To select oral cancer cell lines suitable for MMP-11 knockdown experiments, we examined the MMP-11 protein and mRNA in five oral cancer cell lines (HSC3, SAS, SCC9, SCC25 and TW2.6) by Western blot and qRT-PCR analysis." (PMID 25423087, 2014). "Except for oral cancer, overexpression of plasma MMP-11 has also been demonstrated as a useful marker for diagnosis, prognosis and treatment in other cancers." (PMID 25423087, 2014). "MMP-11 over-expression has been demonstrated in human cancers including oral cancer, desmoid tumors, non-small cell lung cancer and esophageal adenocarcinoma." (PMID 21513571, 2011). "The MMP-11 increased cell motility of oral cancer cells through the focal adhesion kinase/SRC kinase pathway, and it is plausible that this pathway could be involved in BC metastasis." (PMID 37798646, 2023). "Moreover, treatment with the MMP-11 shRNA exerted an inhibitory effect on migration in SCC9 oral cancer cells." (PMID 25423087, 2014). "Furthermore, in vitro study also showed that MMP-11 knockdown had an inhibitory effect on migration in SCC9 oral cancer cell." (PMID 25423087, 2014). "In addition, the metastatic effects of the MMP-11 knockdown on the oral cancer cells were investigated by cell migration assay." (PMID 25423087, 2014). "Besides, they also concluded that the advanced expression of paxillin, FAK, and MMP-11 could strongly increase the incidence of oral cancer metastasis." (PMID 39048985, 2024). "Moreover, to test the biological effects of reduced expression of MMP-11 protein on OSCC cell, migration assay of oral cancer cell line with knockdown MMP-11 was conducted, and demonstrated treatment with the MMP-11 shRNA exerted an inhibitory effect on migration in SCC9 oral cancer cells." (PMID 25423087, 2014). "Our data showed that MMP-11 expression was significantly higher in SCC9 and SAS, as compared to the one in HSC3, SCC25 and TW2.6 oral cancer cell." (PMID 25423087, 2014).
lung adenocarcinoma (6 papers, 2021 to 2025). A carcinoma that arises from the lung and is characterized by the presence of malignant glandular epithelial cells. "In the following, to further analyze the differences in MMP11 expression at the mRNA level in lung adenocarcinoma tissues under different EGFR mutation conditions, we obtained 512 samples with known EGFR mutation conditions from the TCGA-LUAD dataset." (PMID 36756152, 2023). "Since different EGFR mutation subtypes may have different biological behavioral functions, we further analyzed the differences in MMP11 expression levels in different EGFR mutation subtypes of lung adenocarcinoma." (PMID 36756152, 2023). "To further analyze the possible pathways and mechanisms of MMP11 affecting immune response in EGFR mutant lung adenocarcinoma, we analyzed the differential genes between high and low MMP11 expression groups in EGFR mutant lung adenocarcinoma." (PMID 36756152, 2023). "This suggests that high expression of MMP11 in EGFR-mutant lung adenocarcinoma suggests a poor immune response and has some unique significance." (PMID 36756152, 2023). "We found that in EGFR mutant lung adenocarcinoma, Tregs cells were infiltrated to a greater extent in the MMP11 high expression group (red, n=46) compared to the MMP11 low expression group (blue, n=20) (P < 0.05)." (PMID 36756152, 2023). "Thus the mechanism regarding the role of EGFR and MMP11 in regulating immunity in lung adenocarcinoma is worthy of further exploration." (PMID 36756152, 2023). "Likewise, a previous study has shown that knockdown of MMP11 can hamper cancer progression in lung adenocarcinoma cells as well as impeding tumor growth in xenograft models." (PMID 33836753, 2021). "MMP11 has been proposed to be a hub cancer driver gene in lung adenocarcinoma." (PMID 33836753, 2021). "Consequently, MMP11 is related to the immunological microenvironment of EGFR-mutant lung adenocarcinoma, which may be a predictor of possible immunotherapeutic response." (PMID 36756152, 2023). "We found that MMP11 expression in lung adenocarcinoma did not correlate with cytotoxic T-cell level (P = 0.192)." (PMID 36756152, 2023). "The pathway between EGFR and MMP11 in lung adenocarcinoma has not been investigated yet, but there are some results on the pathway related to MMP11 in other tumors." (PMID 36756152, 2023). "In the exploration of the correlation between MMP11 and immune response, we found that MMP11 expression in lung adenocarcinoma did not correlate with cytotoxic T-cell level and the clinical benefit of ICB therapy regardless of whether EGFR is mutated or not." (PMID 36756152, 2023).
osteosarcoma (6 papers, 2019 to 2024). A usually aggressive malignant bone-forming mesenchymal neoplasm, predominantly affecting adolescents and young adults. "Overexpression of miR-192 can downregulate matrix metallopeptidase 11 (MMP-11) expression, promote apoptosis, and reduce the proliferation, migration, and invasion of osteosarcoma (OS) cells." (PMID 37170506, 2023). "Inhibition of MMP-11 (also known as stromelysin-3) in MG‐63 and U2OS osteosarcoma cells by upregulating the micro RNA-125a-5p has proved the important function of another MMP during the migration and invasion process." (PMID 32377334, 2020). "Furthermore, the upregulation of matrix metallopeptidase genes, including MMP1, MMP2, MMP9, MMP11, and MMP16, has been observed in osteosarcoma (OS)." (PMID 38966281, 2024).
endometriosis (5 papers, 2020 to 2025). The growth of functional endometrial tissue in anatomic sites outside the uterine body. "This supports the presence of MMP11 in both subtypes of endometriosis, with a slightly higher upregulation of MMP11 in DE." (PMID 39373851, 2024). "This indicates strong potential for MMP11 to use as a universal target for visualization of endometrial glands and stroma for endometriosis surgery." (PMID 39373851, 2024). "MMPs, and MMP11 specifically, were expressed in several types of endometriosis and showed a higher expression level in ectopic endometrium compared to eutopic endometrium." (PMID 39373851, 2024). "Immunohistochemical evaluation of ten potential biomarkers to use as a target in fluorescence guided surgery in endometriosis surgery showed MMP11 and VCAN to be the most promising biomarkers." (PMID 39373851, 2024). "MMP11 was significantly up-regulated for the up-regulated expression genes, suggesting that endometrial cells in patients with endometriosis present a mechanical phenotype of tissue remodeling." (PMID 33868805, 2021). "Overexpression of MMP11 is reported in the literature for both adenomyosis and endometriosis." (PMID 41272701, 2025). "Furthermore, ECM1 (extracellular matrix protein 1)+ and MMP11 (matrix metallopeptidase 11)+ endometrial-type stroma cells were detected in the endometriosis lesions." (PMID 37353907, 2023). "Next, topological analysis using the cytoHubba plugin in Cytoscape identified MMP7, MMP11, SERPINA1, THBS1, and IGFBP5 as candidate hub genes expressed in both adenomyosis and endometriosis." (PMID 41272701, 2025). "MMP7, MMP9, MMP11, and TIMP1 were observed to be significantly upregulated in women with adenomyosis as compared to endometriosis." (PMID 41272701, 2025). "Out of these, significant overexpression of MMP7, MMP9, MMP11, IGFBP5, and TIMP1 was observed at both gene and protein levels in adenomyosis as compared to endometriosis." (PMID 41272701, 2025). "MMP11 and VCAN showed the largest upregulation in endometriosis compared to adjacent tissue and showed a membranous or extracellular staining pattern." (PMID 39373851, 2024). "For both MMP11 and VCAN, staining was observed in adjacent tissue (MMP11: vessel walls, VCAN: smooth muscle cells, loose connective tissue, vessel walls), however significant less than in endometriosis, resulting in high TIS differences." (PMID 39373851, 2024). "Our study in endometrial cells from women with endometriosis further supports those results and suggests ARNTL and MMP11 may play an important role in the pathogenesis of endometriosis." (PMID 33868805, 2021).
Obesity (5 papers, 2016 to 2023). Accumulation of substantial excess body fat. "Increased MMP11 expression (MMP11Tg) is associated with a lean phenotype and protection from diet-induced obesity, while loss of MMP11 expression (MMP11KO) promotes weight gain and metabolic syndrome." (PMID 32825455, 2020). "Consistently, we showed in a GOF mouse model that MMP11 protects against diet-induced obesity, insulin resistance and hepatic steatosis through increased fatty acid turnover and oxidation." (PMID 37445827, 2023). "The authors suggest that dysregulated MMP11 occurs early in adipose tissue dysfunction, leading to obesity and subsequent insulin resistance." (PMID 37445827, 2023). "In addition to MMP2, our laboratory has demonstrated that MMP14 cleaves the catalytic domain of MMP11, an important regulator of energy metabolism protecting from diet-induced obesity, fatty liver and insulin resistance." (PMID 37445827, 2023). "Hence, MMP11 overexpressing mice were lean, had improved metabolic parameters and were protected from diet-induced obesity; whereas MMP11−/− displayed a phenotype reminiscent of the metabolic syndrome." (PMID 37445827, 2023). "Moreover, Mmp11-Tg mice were protected from diet-induced obesity and display mitochondrial dysfunction, due to oxidative stress, and metabolic switch from oxidative phosphorylation to aerobic glycolysis." (PMID 27126782, 2016). "Interestingly, studies using MMP-11 transgenic (MMP11-Tg) mice and MMP11-/- mice revealed that MMP-11 protects against diabesity (diabetes and obesity) and hepatic steatosis by controlling energy metabolism and increasing fat mobilization and metabolism." (PMID 32414178, 2020).